TNF (tumor necrosis factor)
Diseases named in the same sentence as TNF in open-access papers (continued):
Sharing a sentence is not in itself a finding about the gene and the disease.
dependence (4 papers, 2014 to 2025). "A total of 28 out of the 88 (32%) patients had a history of steroid dependence, and 14 patients (16%) had been exposed to anti-TNFα before admission to our hospital." (PMID 34830694, 2021). "In future studies, it would be interesting to investigate how this affects the recruitment of satellite cells and leukocytes in vivo, and in particular in models of TNF-α-dependent muscle disease." (PMID 24603712, 2014).
diverticulitis (4 papers, 2023 to 2025). An infection that develops in the diverticula of the intestinal tract. "At a molecular level, patients with IBD and diverticulitis were found to have similar levels of the inflammatory protein syndecan-1 (SD1) but significantly higher expression of basic fibroblastic growth factor (bFGF) and tumour necrosis factor (TNF-α) in diverticulitis." (PMID 38831715, 2024).
ductal adenocarcinoma (4 papers, 2019 to 2023). "In experimental animal studies, treatment of ductal adenocarcinoma with TNF-alpha significantly facilitated tumor growth and metastasis, whereas treatment with infliximab and etanercept reduced tumor growth, for instance of liver metastases." (PMID 30696421, 2019). "Similarly, increased expression of TNF-α was proportional to tumor grade and has also been observed in invasive breast ductal carcinomas." (PMID 33292267, 2020).
dysentery (4 papers, 2008 to 2024). Acute inflammation of the intestine associated with infectious diarrhea of various etiologies, generally acquired by eating contaminated food containing toxins, biological derived from bacteria or other microorganisms. "TNF-α increased in all animals after inoculation, with a peak during dysentery, and IL-6 was found in 3 animals during dysentery and in the 2 animals that did not develop clinical signs of disease." (PMID 18700003, 2008). "Blood was sampled before inoculation and repeatedly during acute dysentery and recovery periods and cytokine levels of IL-1β, IL-6, Il-10, TNF-α and IFN-γ were measured by ELISA." (PMID 18700003, 2008). "The aim of the present study was therefore to induce dysentery experimentally in pigs and to monitor the development of some immunoregulatory cytokines (IL-1β, IL-6, Il-10, TNF-α and IFN-γ) in blood collected at various stages of the disease." (PMID 18700003, 2008). "Nonetheless, the presence of TNF-α during the dysentery period may influence the pathogenesis since it can facilitate lesion development and the gastrointestinal tract is known to be sensitive to the presence of this cytokine." (PMID 18700003, 2008).
ependymoma (4 papers, 2017 to 2025). A WHO grade II, slow growing tumor of children and young adults, usually located intraventricularly. "In ependymomas and DIPG IL-6-JAK/STAT, IFN-γ, and TNF-α signaling were enriched." (PMID 28969007, 2017). "To further dissect the molecular mechanism of RELAFUS-driven ependymoma formation, we examined the implication of RELA target genes in the RELAFUS1 transcription network using publicly available Rela ChIP-seq data in murine embryonic fibroblasts (MEFs) after TNF stimulation." (PMID 33685520, 2021).
esophageal tumor (4 papers, 2018 to 2020). "The remarkable association between Tim-3 and TNF-α in both human and murine esophageal tumor tissues further support the important role of TNF-α in Tim-3 expression on NK cells." (PMID 31109341, 2019). "More importantly, there is a significant correlation between TNF-α and Tim-3 expression in esophageal tumor tissues." (PMID 31109341, 2019). "By contrast, the esophageal tumor size and serum levels of IL-1β, IL-4, IL-13 and tumor necrosis factor-alpha (TNF-α) were not significantly affected by adding açaí to the diet for 35 weeks." (PMID 29966007, 2018).
eye inflammation (4 papers, 2020 to 2025). "Adalimumab, a tumour necrosis factor (TNF)-alpha inhibitor, effectively controls joint and eye inflammation; however, its long-term use may increase the risk of adverse health outcomes and place an undue financial burden on the patient and healthcare system given its high cost." (PMID 33109240, 2020). "Because of uncontrolled eye inflammation, treatment by anti-TNFα was decided for 13 (18%) patients (cases)." (PMID 35311049, 2022). "Several studies have shown that anti-TNFα is not only efficient in controlling severe children eye inflammation, but it is also safe to use, with a low rate of severe side effects now well-known and treatable." (PMID 35311049, 2022). "IL-17 from Th17 cells stimulates the production of ROS, NO, TNF-α, and IL-1β in neutrophils, enhancing neutrophil extracellular trap (NET) formation, which significantly contributes to the ongoing eye inflammation." (PMID 39839752, 2025).
filariasis (4 papers, 2012 to 2022). "infection when co-infected with filariasis, according to the association with a higher IL-10/TNF-α ratio, and when co-infected with intestinal parasites, according to the association with a higher IL-10/IL-6 ratio." (PMID 35421083, 2022). "Next, stimulated PBMCs were investigated for their TNF production since during filariasis this cytokine has been shown to be a feature of acute infection." (PMID 22509424, 2012). "In recent years, there have been various reports describing the involvement of TNF during filariasis." (PMID 22509424, 2012).
G6PD deficiency (4 papers, 2015 to 2021). An X-linked genetic condition caused by alterations in the gene G6PD that result in moderately to severely decreased activity levels of the enzyme glucose-6-phosphate dehydrogenase. "To further understand the role of cytokines in the context of G6pd deficiency, we measured the expression of TNF-α, IFN-γ, IL-1β, IL-6, IL-12, TGF-β and IL-10 along with cytokine levels in serum and mRNA expression in spleen." (PMID 34456927, 2021). "Previous studies have shown that peripheral blood mononuclear cells from human subjects with G6PD-deficiency exhibit reduced secretion of inflammatory cytokines such as TNFα and IL-1β." (PMID 31805953, 2019). "The effect of G6PD deficiency on the COX-2 expression transcriptional level upon TNF-α treatment was determined." (PMID 27097228, 2016).
gastroparesis (4 papers, 2021 to 2025). Paralysis of the muscles of the stomach wall resulting in delayed emptying of the gastric contents into the small intestine. "The levels of several cytokines, including serum TNFα and IL-6, are elevated in gastroparesis patients." (PMID 37033595, 2023). "At baseline, patients with gastroparesis symptoms exhibited increased levels of interleukin-6 (IL-6) (46.64 to 53.01 pg/mL) and tumor necrosis factor-alpha (TNF) (22.18 to 7.46 pg/mL) (normal Interleukin-6 10.1 pg/mL and TNF 7.1 pg/mL, respectively)." (PMID 34584813, 2021). "Previous studies in humans and animals with gastroparesis, IBS, FD, and IBD have reported increased levels of pro-inflammatory cytokines such as interleukin (IL)-1β, IL-6, IL-8, and tumor necrosis factor (TNF)-α in the blood and serum." (PMID 37990288, 2023).
generalized pustular psoriasis (4 papers, 2015 to 2024). A rare and extreme form of psoriasis characterized by the appearance of sterile pustules which can take many patterns. "Patients with generalized pustular psoriasis showed the greatest rates of improvement or resolution of disease when the anti-TNF therapy was switched or discontinued." (PMID 39781163, 2024). "She had been receiving anti-TNFα therapy with infliximab because of generalized pustular psoriasis for 3 years, but her skin symptoms worsened following withdrawal during pregnancy." (PMID 32842976, 2020).
gingival overgrowth (4 papers, 2010 to 2025). Excessive growth of the gingiva either by an increase in the size of the constituent cells (gingival hypertrophy) or by an increase in their number (gingival hyperplasia). "In order to investigate the impact of the inflammatory component in the pathogenesis of amlodipine-induced gingival enlargement, we examined the relative gene expression of IL-6 and TNF-α." (PMID 39204180, 2024). "Whereas this function of TNF-α is likely to be important in the pathogenesis of tissue-destructive diseases such as druginduced gingival overgrowth, it is clear that the production of TNF-α induced by RANTES relates to the risk of fibrosis." (PMID 20871770, 2010). "The proinflammatory cytokine TNF-α showed increased expression in druginduced gingival overgrowth, which could also contribute to the enhanced effect of cyclosporine on collagenous protein synthesis by gingival fibroblasts." (PMID 20871770, 2010). "Specifically, IL-6 and TNF-α expression levels were lower in patients taking amlodipine compared to those with gingival enlargement who were not taking amlodipine." (PMID 39204180, 2024). "IL-6, TNF-α, ST2, and FGF-2 expression levels were lower in patients taking amlodipine, with and without gingival enlargement." (PMID 39204180, 2024).
hand osteoarthritis (4 papers, 2014 to 2024). "We tested the potential of circulating galectin-1, interleukin (IL)-1 beta, IL-6, and tumour necrosis factor alpha (TNF alpha) levels at baseline in individuals with knee pain as biomarkers for development of radiographic knee and/or hand osteoarthritis (OA)." (PMID 38469554, 2024). "Three databases were searched for randomized controlled trials examining the efficacy of TNF inhibitors in hand osteoarthritis." (PMID 37649531, 2023). "This study aimed at systematically review the evidence for the efficacy of Tumor Necrosis Factor (TNF) inhibitors on symptoms and structural outcomes in hand osteoarthritis." (PMID 37649531, 2023). "However, a systematic review on the efficacy of TNF inhibitors in hand osteoarthritis, administered subcutaneously rather than intra-articularly, found no significant impact on pain or grip strength over the short-term (4–6 weeks) or longer-term (12 months) periods." (PMID 39457530, 2024).
hemoglobinopathies (4 papers, 2020 to 2024). "That plasma levels of 12-HETE and TNF-α levels were significantly increased in severe compared to mild SCD supports the current school of thought that inflammation is an important component of the pathophysiology of this haemoglobinopathy." (PMID 34713264, 2021). "Thus, our results suggest that chemokines CXCL10 and CCL2 and cytokines, TNF-α, IL-8, and IL-6 may contribute to the overall pro-inflammatory response and could be utilized for predicting the severity of Plasmodium infection or a hemoglobinopathy." (PMID 33424841, 2020).
hemorrhagic disease (4 papers, 2014 to 2025). Spontaneous or near spontaneous bleeding caused by a defect in clotting mechanisms (blood coagulation disorders) or another abnormality causing a structural flaw in the blood vessels (hemostatic disorders). "Single-nucleotide polymorphism analysis identified TNF-α polymorphisms at the TNF-308A allele to be a possible risk factor for development of hemorrhagic disease in patients infected with DV." (PMID 25580138, 2014). "Early pro-inflammatory peaks (e.g., IFN-γ, TNF, IL-6) may drive vascular inflammation and tissue damage, contributing to severe clinical signs such as bleeding disorders, where endothelial injury and dysregulated coagulation cascades are involved." (PMID 41039483, 2025). "Consistent with hemorrhagic disease, negative control animals showed signs of liver damage as evidenced by increased levels of liver enzyme AST, and several key cytokines such as IL-1β, IL-6, IL-1Ra, MIP-1α, TNFα, IFN-γ, IL-2, and FGF-β." (PMID 30723475, 2018).
hepatic granuloma (4 papers, 2014 to 2020). A granuloma located in the liver. "Mature hepatic granulomas appeared in Amastin-Gp63 group were consistent with the early high secretion of TNF-α." (PMID 32176727, 2020). "Our findings suggest that BSE-CD treatment attenuates S. japonicum egg-induced hepatic granulomas and fibrosis, at least partly due to reduced NF-κB signaling and the subsequently decreased expression of VEGF, TNF-α, and MCP-1." (PMID 24941000, 2014). "In conclusion, our data show that BSE-CD treatment can attenuate S. japonicum egg-induced hepatic granulomas and fibrosis, which might be partly due to the suppression of the NF-κB pathway and a decreased expression of VEGF, TNF-α and MCP-1." (PMID 24941000, 2014).
hepatoblastoma (4 papers, 2007 to 2022). Hepatoblastoma (HB) is a malignant hepatic tumor and is the most common pediatric liver cancer. "There have been other molecules that participate in Wnt/β-catenin triggered signaling pathway in hepatoblastoma including tumor necrosis factor-α (TNF-α), regenerating islet-derived 1 and 3 α (REG1A and 3A), substance P (SP)/neurokinin-1 receptor and PARP-1." (PMID 31511432, 2019). "It suggests that increase in β-catenin may produce its cellular proliferative effects in hepatoblastoma due to inhibition of TNF-α-induced apoptosis." (PMID 31511432, 2019). "The activation of β-catenin signaling may trigger the activation of other signaling pathways to induce the development of hepatoblastoma, which may include inhibition of TNF-α-dependent apoptosis, increase in the secretion of epithelial growth factor and formation of complex of with YAP-1 protein." (PMID 31511432, 2019). "The activation of β-catenin signaling may trigger the activation of other signaling pathways to induce the development of hepatoblastoma, including inhibition of TNF-α-dependent apoptosis, increase in the secretion of epithelial growth factor and formation of complex of with YAP-1 protein." (PMID 31511432, 2019). "As a model application, the method was applied to identify the genes that play a role in the cytotoxic responses of human hepatoblastoma cell line (HepG2) to saturated fatty acid (SFA) and tumor necrosis factor (TNF)-α, as compared to the non-toxic response to the unsaturated FFAs (UFA) and TNF-α." (PMID 19052637, 2008).
hyperaldosteronism (4 papers, 2015 to 2024). Overproduction of aldosterone by the adrenal glands, which may lead to hypokalemia and/or hypernatremia. "These evidences explain the current association of hyperaldosteronism and CRP, adipocytokine release of TNF-α, IL-6 & IL-23 as well as adhesion endothelial markers; ICAM and VCAM and p-selectin." (PMID 27478508, 2016).
hyperreactivity (4 papers, 2010 to 2015). "TNF-alpha is produced by epithelium, mast cells, macrophages, and induces the migration and the activation of leukocytes and airway hyperreactivity." (PMID 26569396, 2015). "To determine if TNF-α also contributed to both AHR and mucus hypersecretion, or if distinct immunological mechanisms mediate separate disease manifestations, we evaluated both histology and airway hyperreactivity." (PMID 25769044, 2015).
Hypothermia (4 papers, 2011 to 2023). Reduced body temperature due to failed thermoregulation. "Hypothermia can lower brain metabolism and cerebral blood flow while reducing pro-inflammatory factors like IL-6 and TNF-α." (PMID 38178890, 2023). "Hypothermia has been found to decrease inflammation by decreasing both the infiltration of polymorphonuclear cells and the production of a wide range of inflammatory proteins such as TNF-α, IL-1b, IL-6, and macrophage inflammatory protein-2." (PMID 27583464, 2016). "Hypothermia and locomotor hypoactivity were induced by LPS>IL-1β>TNF-α>>IL-6." (PMID 23840908, 2013). "Hypothermia is known to occur in C57BL/6 mice when at ambient temperatures of 20-22°C and while the molecular underpinning of this hypothermic response is less clear it is nonetheless known that both systemic IL-1β and TNF-α can induce this response." (PMID 21586125, 2011).
infectious colitis (4 papers, 2013 to 2019). A viral or bacterial infectious process affecting the large intestine. "In contrast, the mice were even more susceptible to infectious colitis, suggesting a rather beneficial function on TNFα signalling during C. rodentium infection." (PMID 30995806, 2019). "We studied the impact of administering XPro1595, a novel antagonist of soluble tumor necrosis factor-α(TNFα), on the regulation of hepatic cytochrome P450 enzymes in the Citrobacter rodentium model of infectious colitis." (PMID 24707356, 2014). "In conclusion, our results support previous work indicating a selective in vivo role for TNFα in the suppression of Cyp3a11 and Cyp3a25 in a model of acute infectious colitis." (PMID 24707356, 2014). "As a first step, we evaluated the expression of the pro-inflammatory cytokines IL-8 and TNF-alpha to confirm and define the degree of inflammation in the inflamed biopsies of IBD patients and patients with infectious colitis." (PMID 24257430, 2013). "The mRNA expression of inflammatory cytokines (IL-8 and TNF-α), an apoptosis marker (caspase 3) and PHD1, 2 and 3 was analysed in biopsies of IBD patients (UC and CD), patients with infectious colitis and healthy controls using qRT-PCR." (PMID 24257430, 2013). "Interestingly, during C. rodentium infection in mice, TNFα is increased in the gut, however the absence of TNFα signalling due to Tnfr knockout in this model did not protect animals from infectious colitis." (PMID 30995806, 2019).
intrahepatic cholestasis (4 papers, 2014 to 2025). A cholestasis characterized by impairment of the bile flow caused by obstruction located in the liver. "In the present study, it was investigated whether HMGB1 is released from cholangiocytes to induce cholangiole inflammation and the exacerbation of intrahepatic cholestasis in ACLF and if such a release can be induced by lipopolysaccharide (LPS) or tumor necrosis factor-α (TNF-α) in vitro." (PMID 25187820, 2014).
ischemic disease (4 papers, 2016 to 2022). Lack of blood supply to an area of the body, resulting in impairment of tissue oxygenation. "TNF-α and IL-10 are known to be pro- or anti-inflammatory cytokines in ischemic diseases and its animal models." (PMID 31419236, 2019). "In this study, we generated EMV from HBMEC under TNF-α plus SD stimulation to mimic ischemia and inflammation in ischemic diseases, and examined the functional role of these EMV on HBVSMC." (PMID 28127288, 2016). "In addition, BA can alleviate oxygen-glucose-deprived challenged microglia injury in ischemic diseases by attenuating expression of inflammatory cytokines TNF-α, IL-1β, IL-6, and IL-8 through TLR4 pathway." (PMID 36408278, 2022).
jejunoileitis (4 papers, 2013 to 2024). "In previous investigations, it was observed that the production of TNF-α has the potential to enhance the production of nitric oxide (NO) through the overexpression of iNOS in indomethacin-induced jejunoileitis." (PMID 38355510, 2024). "Previous studies showed that TNF-α production could increase nitric oxide (NO) production by iNOS overexpression in indomethacin-induced jejunoileitis." (PMID 33530540, 2021). "Moreover, in a model of indomethacin-induced jejunoileitis in rats, it has been shown that treatment with TNF antibody reduces iNOS expression, suggesting that TNF-α may directly modulate iNOS expression." (PMID 29360756, 2018).
kidney transplant (4 papers, 2011 to 2024). A surgical procedure in which one or both kidneys from a donor are implanted into a recipient. "Indeed serum levels of inflammatory cytokines such as TNF-α were described to be higher in kidney transplant patients and increased significantly during allograft rejection." (PMID 22039526, 2011). "In terms of the impact of IL2 -330T > G, IL10 -1082G > A, and TNF -308G > A on BPAR incidence, our results are in accordance with previous meta-analyses indicating these SNPs are not significant determinants of BPAR incidence in Caucasian kidney transplant recipients receiving TAC or ciclosporin." (PMID 32153387, 2019).
kidney tumor (4 papers, 2014 to 2024). "We also observed that pediatric kidney tumor cell lines exhibit the functional expression of an additional cytokine signaling pathway, the tumor necrosis factor (TNF)-α-mediated activation of nuclear factor kappa B (NF-κB)." (PMID 38396958, 2024). "However, we could not observe the elevated expression of IFN-γ or TNF-α, which were reported to be increased by cryoablation in a model of kidney tumor." (PMID 25821968, 2015).